DUSP3 (dual specificity phosphatase 3)
Diseases named in the same sentence as DUSP3 in open-access papers (continued):
Sharing a sentence is not in itself a finding about the gene and the disease.
tumor (15 papers, 2014 to 2025). "We have studied the tumor-promoting ability of DUSP3 deficiency by examining the onset of LAC in DUSP3 +/+ and DUSP3−/− mice with or without the EGFR-Del Tg gene." (PMID 35705979, 2022). "The same group investigated the function of DUSP3 in tumor-associated macrophages in a Lewis Lung carcinoma (LLC) metastasis model, where DUSP3−/− macrophages displayed enhanced recruitment to LLC-bearing lungs and promoted metastatic tumor growth." (PMID 31159473, 2019). "Moreover lung weight and lung tumour area were significantly higher in DUSP3-/-→DUSP3+/+ mice compared to DUSP3+/+→DUSP3+/+ mice suggesting that DUSP3-deficient hematopoietic cells contribute to enhance LLC tumour aggressiveness." (PMID 29020102, 2017). "In this study, we examined the expression levels of DUSP3 in normal and tumor tissues and discovered that DUSP3 was markedly downregulated in tumor cells and tissues." (PMID 39744427, 2025). "The results showed a decrease in DUSP3 expression in the order of well, moderately, and poorly differentiated tumor groups." (PMID 39849581, 2025). "The DUSP3-/- macrophages as well as bone marrow monocytes are more easily recruited to LLC tumour-conditioned medium than DUSP3+/+ monocytes and macrophages, possibly explaining the higher number of monocyte/macrophages found in DUSP3-/- LLC-bearing lungs." (PMID 29020102, 2017). "Considering the importance of angiogenesis in metastasis formation, our study aimed to investigate the role of DUSP3 in tumour cell dissemination." (PMID 29020102, 2017). "We therefore quantified proliferating tumour cells using anti-Ki67 on lungs sections from DUSP3-/- and DUSP3+/+ tumours bearing mice." (PMID 29020102, 2017). "Haematoxylin-eosin staining of lung sections and tumour area quantification confirmed that DUSP3-/- lung tumours were significantly larger than in DUSP3+/+ lungs." (PMID 29020102, 2017). "These observed differences suggest that the accelerated metastasis growth in DUSP3-/- is tumour-model dependent." (PMID 29020102, 2017). "We found that Ki67+ cells number was significantly higher inside tumour zones of lungs from DUSP3-/- compared to DUSP3+/+ mice." (PMID 29020102, 2017). "We performed a similar analysis on tumour-bearing lung cell suspensions of DUSP3+/+ and DUSP3-/- mice." (PMID 29020102, 2017). "Compared to vehicle liposome-treated mice, elimination of macrophages decreased significantly LLC metastatic dissemination in both DUSP3+/+ and DUSP3-/- mice as demonstrated by the decreased bioluminescence, weight and tumor area in lungs." (PMID 29020102, 2017). "We showed that matrigel plugs and LLC subcutaneous tumours were less vascularized in DUSP3-/- mice compared to DUSP3+/+ littermates." (PMID 29020102, 2017). "DUSP3-/- bone marrow transfer to lethally irradiated DUSP3+/+ mice was sufficient to transfer the phenotype to DUSP3+/+ mice, indicating that hematopoietic cells compartment was involved in the increased tumour cell dissemination to lung tissues." (PMID 29020102, 2017). "We next investigated the angiogenic role of DUSP3 in the context of tumor development by using a rapid tumor-induced model." (PMID 24886454, 2014). "We already described the tumor promoting effect of cathepsin K, and of lysine demethylase Kdm2a in LC which stimulates Erk1/Erk2 signaling through epigenetic silencing of DUSP3." (PMID 38245882, 2024). "We demonstrated that downregulation of DUSP3 in MDA-MB-231 or SUM159 could also enhance the phosphorylation of ERK which might be one of the mechanism that miR-1915-3p regulates the tumor cells." (PMID 30048472, 2018). "Interestingly, we found a higher percentage of tumour-promoting Ly6Cint macrophages in DUSP3-/- LLC-bearing lung homogenates that was at least partially due to a better recruitment of these cells." (PMID 29020102, 2017). "The second plausible premise could be that LLC and E0771-metastatic cells respond differently to the DUSP3-/- tumour microenvironment." (PMID 29020102, 2017).
tumor (continued). "Consequently, it will be interesting to further investigate the precise signalling pathway implicating DUSP3 in the enhanced LLC tumour cell dissemination to lung tissues and the exact molecular role of DUSP3 in this event." (PMID 29020102, 2017). "We have previously shown that DUSP3 plays an important role in tumour neo-vascularisation." (PMID 29020102, 2017). "However, accumulating evidence points to a possible role of DUSP3 as a tumour suppressor." (PMID 40943262, 2025). "To further assess which hematopoietic cell populations could be involved in the increased tumour aggressiveness, we analysed, in first instance, by flow cytometry, the myeloid cell subsets present in established DUSP3+/+ and DUSP3-/- lung homogenates bearing LLC tumours." (PMID 29020102, 2017). "In fact, although these macrophages did not influence in vitro LLC proliferation or migration, they may be responsible for the enhanced in vivo LLC proliferation as judged by the significant increase of Ki67+ cells in DUSP3-/- lungs bearing tumours compared to the control lungs." (PMID 29020102, 2017). "On the other hand, recent reports showed that DUSP3 is downregulated in NSCLC and when overexpressed in these cells, it leads to decreased cell proliferation and reduced tumor growth in a xenograft mouse model." (PMID 24886454, 2014). "In NSCLC, it has been reported that DUSP3 expression is epigenetically repressed by the histone H3 lysine 36 demethylase KDM2A (also called FBXL11 and JHDM1A), which is frequently overexpressed in NSCLC tumours and cell lines, and the high level of expression of which correlates with poor prognosis." (PMID 40943262, 2025). "However, we found that DUSP3-deficiency prevented neo-vascularisation of Matrigel plugs and LLC xenograft tumors suggesting that DUSP3 plays an important and non-redundant function in tumor-induced angiogenesis." (PMID 24886454, 2014).
infection (2 papers, 2014 to 2024). The state of being infected such as from the introduction of a foreign agent such as serum, vaccine, antigenic substance or organism. "Three of these genes (Dcaf7, Dusp3, and Psme3) were down-regulated in susceptible vs. resistant mice at both pre- and post-infection time points by qPCR." (PMID 24901344, 2014). "Five genes in the QTL (Dcaf7, Dusp3, Fam134c, Psme3, and Slc4a1) were significantly differently expressed in a) susceptible vs. resistant mice, and b) humans with S. aureus blood stream infection vs. healthy human subjects." (PMID 24901344, 2014). "In our experiment, VEGF was also significantly elevated in Dusp3 siRNA transfected RAW264.7 macrophages in both non-infection and S. aureus infection condition." (PMID 24901344, 2014).
DUSP3 also shares sentences with these, for which no sentence is quoted: cervix cancer (3 papers); prostate carcinoma (2); acute kidney injury (1); aneurysm (1); aortic aneurysm (1); atherosclerosis (1); atrial fibrillation (1); chondrodysplasia (1); colorectal cancer (1); COVID-19 (1); diabetic retinopathy (1); endocarditis (1); gastric cancer (1); gastrointestinal infection (1); heart failure (1); influenza (1); leukemia (1); lung (1); non-alcoholic steatohepatitis (1); psoriasis (1); pulmonary hypertension (1); pulmonary TB (1); respiratory infection (1); septic shock (1); small cell lung carcinoma (1); squamous intraepithelial lesions (1); steatosis (1); viral infections (1).